CRP (C-reactive protein)
Diseases named in the same sentence as CRP in open-access papers (continued):
Sharing a sentence is not in itself a finding about the gene and the disease.
Alzheimer disease (continued). "One such candidate might be statin therapy, administration of which has been found to attenuate circulating CRP concentration and has also been associated with a reduction in cognitive symptoms among individuals with Alzheimer’s disease." (PMID 28694011, 2017). "In addition, conditions associated with aging were represented, including variants linked to Alzheimer’s disease, age at menopause, bone density, Myositis, Parkinson’s disease, macular degeneration, C-reactive protein levels and longevity." (PMID 28957414, 2017). "In addition to these genotype-dependent effects on lipids and CRP levels, ε4 is associated with infectious diseases and a high risk of age-related cardiovascular and Alzheimer disease." (PMID 27177774, 2016). "Although it has not been determined whether subclinical systemic inflammation is associated with neuroinflammation, individuals with subclinically high CRP levels were found to be at increased risk of developing Alzheimer’s disease." (PMID 26308525, 2015). "CRP, again, seems to activate the complement system in brains and may lead to chronic neuroinflammation which then may cause neuronal death in Alzheimer's disease." (PMID 24799767, 2014). "Although GWAS studies have reported significant associations between rs2075650 and Alzheimer's disease, brain imaging, total cholesterol, and CRP plasma levels, no analyses were performed to determine whether these associations are APOE independent." (PMID 21418511, 2011). "Interestingly, the rs4420638 SNP associated with Lp-PLA2 activity in our study has also been associated with LDL-C, Alzheimer's disease, and C-reactive protein in other genome-wide association studies." (PMID 20442857, 2010). "Immunoreactivity of CRP in neurofibrillary tangles of Alzheimer’s disease evidenced that LGI was involved in neurodegenerative diseases progression." (PMID 39064755, 2024). "For example, C-reactive protein (CRP) and Alzheimer’s disease were causally linked in 2 methods (MR Egger and IVW) which has been previously noted in previous non-MR studies." (PMID 39006413, 2024). "It was also reported that levels of peripheral cytokines, such as IL-1β, TNF-α, IL-6, and C reactive protein, were significantly higher in elderly with Alzheimer’s disease." (PMID 37623235, 2023). "An inverse relationship between CRP levels and onset of Alzheimer's disease has also been observed, whereby in adults >70.6 years, higher CRP was protective, but in adults aged 60–70.5 years it was adverse." (PMID 39081969, 2023). "They assessed the cognition and measured serum IL-10 and inflammatory markers (C-reactive protein, TNFα) of 60 patients with mild and severe Alzheimer's disease at the beginning of the study and at 6 months." (PMID 36873050, 2023). "C-reactive protein (CRP), a biomarker of systemic inflammation in peripheral blood, has been associated with the development of Alzheimer disease." (PMID 26308525, 2015). "Affected brain areas in patients with Alzheimer disease have been found to contain both activated microglia and CRP." (PMID 26308525, 2015). "CRP is synthesized in the liver and is then transported to accumulate, or is synthesized in neurons, in neurodegenerative lesions in the brains of Alzheimer’s disease patients." (PMID 26218286, 2015). "Studies have shown that Alzheimer’s disease patients with increased chronic inflammation have elevated levels of CRP and SAA in the brain." (PMID 24044608, 2013). "An inflammatory state has been documented in senile plaques and surrounding glia with an increased expression of the acute phase protein CRP as well as pro-inflammatory interleukins such as IL-6 and IL-1 in Alzheimer's disease (AD) patients and animal models." (PMID 20205886, 2010). "Interestingly, elevated CRP levels have been observed in patients with various neurodegenerative diseases, including Alzheimer’s disease (AD) and Parkinson’s disease (PD)." (PMID 40534869, 2025).
Alzheimer disease (continued). "Thus, resveratrol intake improved the total antioxidant status, decreased the deterioration from Alzheimer’s disease, decreased the C-reactive protein concentrations, and, along with quercetin, decreased blood pressure." (PMID 38258063, 2023). "Risk of developing Alzheimer disease is elevated in CGs versus non-CGs (up to 6 times greater), and CGs have increased peripheral inflammatory biomarker levels (eg, C-reactive protein)." (PMID 35700020, 2022). "Some clinical studies have found an increase of CRP whey levels (a protein involved in the acute phase of inflammation that increases during systemic inflammation) and other inflammatory markers in patients who have progressively developed Alzheimer’s disease." (PMID 32054121, 2020). "Clinical follow-up and treatment of high levels of C-reactive protein may be beneficial for prevention of Alzheimer disease in ApoE4 carriers." (PMID 30646251, 2018). "Previous studies have reported a causal relationship between systemic inflammation and functional changes in the brain, such as “sickness behavior”, as well as microglia activation in affected brain areas in Alzheimer disease, together with the generation of CRP in these brain lesions." (PMID 26218286, 2015). "CRP and complement proteins were also detected in cerebral lesions in Alzheimer's disease." (PMID 24799767, 2014). "Finally, our study identified CRP that is increased in brain tissue from Alzheimer’s disease patients and that should be considered not only as a marker but also as a driver of neuroinflammation, since CRP can bind to the complement factor 1q (C1q) and activate the classical complement cascade." (PMID 34335238, 2021). "Importantly, anti-pentraxins drugs (CPHPC and dezamizumab) targeting human SAP have recently entered in clinical phase 2 trial for treatment of amyloidosis and Alzheimer's disease, and human CRP inhibitor targeting CRP-driven complement activation-mediated tissue damage is also being developed." (PMID 30619374, 2018). "Established markers of Alzheimer’s disease and neurodegeneration, including TREM2, SAA1, CHIT1, CRP and PDGFRB demonstrated strong correlations (r > 0.8) in the comparison with SomaLogic measurements." (PMID 41250190, 2025). "Previous findings have illustrated the correlation of high FIB with Alzheimer’s disease and vascular dementia, rather than CRP, which are consistent with our findings and further highlight the vascular property of FIB involved in POCI." (PMID 40040915, 2025). "On the other hand, the Verrucomicrobia phylum was found to be increased in Parkinson’s disease and Alzheimer’s disease, so research has correlated it with increased levels of LPS and consequently of proinflammatory factors such as TNFα, IL6, and C-reactive protein (CRP)." (PMID 41149051, 2025). "It is worth emphasizing, however, that CRP is the most common marker of an acute condition, so if a patient with Alzheimer’s disease changes to chronic, this marker will not be useful because the concentration of CRP usually normalizes within 24 h." (PMID 37047492, 2023). "In addition, in a model of Alzheimer’s disease in mice, treatment with hesperidin (40 mg/kg, 90 days intragastric) increased HO1 and decreased levels of TNFα, CRP, NF-κB and MCP1, suppressing oxidative stress and inflammation." (PMID 33799833, 2021). "C-reactive protein (CRP) is a routine laboratory marker for inflammation but was not increased in serum of patients with Alzheimer disease." (PMID 34204545, 2021). "We also found evidence of an association between the PRS for Alzheimer’s disease (including theApoE region) and HDL, non-HDL, CRP, and triglyceride levels, but the direction of effect was not consistent across all time-points." (PMID 31984241, 2019). "Our findings revealed that peripheral CRP level was not increased but IL-1β was significantly raised in elderly with Alzheimer’s disease as compared to controls before Bonferroni adjustment." (PMID 30104698, 2018).
Alzheimer disease (continued). "CRP gene variation affects early SP development in prodromal Alzheimer's disease, independent of APOE genotype." (PMID 21831326, 2011). "Pentameric C-reactive protein (CRP/hsCRP) and its counterpart interleukin-6 (IL-6 are key acute-phase reactants recognized as biomarkers and potential mediators at the interface between systemic autoimmune inflammation and neurodegenerative disease, particularly Alzheimer’s disease (AD)." (PMID 41373439, 2025). "However, in a meta-analysis, compared with controls, only IL-1β was significantly elevated in Alzheimer’s disease but not IL-6, TNF-α or CRP and the significance did not survive Bonferroni-correction." (PMID 37467176, 2023). "However, elderly with Alzheimer’s disease only had significantly higher peripheral levels of IL-1β (p = 0.047) but not IL-6 (p = 0.138), TNF-α (p = 0.735) or CRP (p = 0.0712)." (PMID 30104698, 2018). "While we included leptin, IL-6, IL-1β, TNF-α, and CRP, we did not assess other cytokines such as MCP-1, IL-18, or markers of microglial activation and phenotype (e.g., CD68 and sTREM2), which may play significant roles in glial reactivity in Alzheimer's disease." (PMID 40521397, 2025).
osteoarthritis (110 papers, 2006 to 2026). A noninflammatory degenerative joint disease occurring chiefly in older persons, characterized by degeneration of the articular cartilage, hypertrophy of bone at the margins and changes in the synovial membrane. "Recent studies have explored the relationship between biomarkers of adipose tissue dysfunction and osteoarthritis-related pain, revealing associations with pain intensity, CRP levels, and structural joint damage." (PMID 40026905, 2025). "Our findings support this translational approach by demonstrating the discriminatory value of certain markers—particularly SII and CRP—in differentiating patients with high fracture risk from those with advanced osteoarthritis." (PMID 41009701, 2025). "AGT was observed to have a strong association with the risk of osteoarthritis (OR 3.12, 95%CI: 1.88–5.19), which remained significant even after additional adjustment with BMI, TG, sleep, IL-6, IL-1β, and CRP levels (OR 2.73, 95%CI:1.63–4.72)." (PMID 34073132, 2021). "Osteoarthritis (OA) is characterized by inflammation of the knee joint, which is caused by accumulation of cytokines and C-reactive protein (CRP) in the extracellular matrix as an early immune response to infection." (PMID 26933405, 2015). "Chronic conditions such as osteoarthritis, even if subclinical, are more likely in obese persons and can lead to elevated CRP, apart from inflammation caused directly by adipose tissue metabolism." (PMID 22558327, 2012). "Serum CRP levels are often higher in those with osteoarthritis and are associated with joint pain, as well as the severity and progression of the disease." (PMID 19682376, 2009). "With regard to the invasiveness of the approaches to the hip joint, previous studies on THA in patients with osteoarthritis (OA) have assessed muscle damage, inflammation, and blood loss by comparing differences in serum levels of creatine kinase (CK), C-reactive protein (CRP), and hemoglobin (Hb)." (PMID 39145606, 2024). "By contrast, the MR analysis of plasma CRP values showed a distinct effects profile in which higher CRP concentrations were associated with serum concentrations of hepatocellular enzymes, with osteoarthritis and with total plasma tau concentration." (PMID 39013416, 2024). "Furthermore, C-reactive protein (CRP) is considered to be associated with systemic inflammation, and patients with osteoarthritis may have higher serum CRP levels, which are correlated with symptom severity." (PMID 38774753, 2024). "Elevated CRP levels have been linked to low BMD and greater bone loss in several studies and in osteoarthritis as well." (PMID 41009701, 2025). "Biomarker levels in other bone and joint inflammatory conditions, such as RA and osteoarthritis (OA), have shown marked elevations in CRP and TNF-α45,46." (PMID 40595978, 2025). "Low-grade inflammation is common in patients with osteoarthritis (OA), and several pro-inflammatory markers, such as interleukin-6 (IL-6) and C-reactive protein (CRP), have been identified as independent predictors of the development of osteoarthritis." (PMID 40257716, 2025). "We therefore identified outcomes significant at the more liberal value of p < 0.05 for both plasma SAP and CRP values, specifically, total brain volume, plasma total tau concentration and osteoarthritis." (PMID 39013416, 2024). "Failure rates were significantly higher for the following variables: revision surgery (p = 0.012) index surgery for reasons other than osteoarthritis (p = 0.01), and C-reactive protein level >30 mg/L (p = 0.042)." (PMID 36140498, 2022). "The anti-inflammatory effects of KrocinaTM have been identified in patients with osteoarthritis by reducing C-reactive protein (CRP) and interleukin (IL)-17 levels." (PMID 35517806, 2022). "Another human study by Schumacher showed that 480 ml tart cherry juice consumption for 6 weeks significantly decreased CRP in adults with mild to moderate osteoarthritis, which supports our finding." (PMID 30678193, 2019).
osteoarthritis (continued). "Our notable results show that Fetuin-A mildly affects the development of osteoarthritis, on the grounds that only IL-2 levels were significantly lower in the Fetuin Group while CRP levels seemed significantly increased in the Fetuin Group." (PMID 31209645, 2019). "Acute phase proteins (APPs), including C-reactive protein (CRP), are elevated in patients’ serum with severe stages of osteoarthritis." (PMID 31209645, 2019). "There is some precedent for MC reducing inflammation in a clinical population; 6 weeks of tart cherry juice supplementation (>900 mg/d polyphenols) reduced serum CRP in those with Kellgren grade 2–3 osteoarthritis." (PMID 31085979, 2019). "In an RCT involving patients with osteoarthritis, Pycnogenol supplementation for 3 months significantly reduced plasma CRP compared with that in the control group; in addition, Pycnogenol reduced plasma free radicals." (PMID 30087862, 2018). "Previous studies have shown that pain intensity from osteoarthritis and sickle cell disease in humans, as well as circulating levels of C reactive protein (CRP; an acute phase inflammatory marker), exhibit peaks in the fall." (PMID 29144407, 2017). "One systematic review provided evidence that the relationship between CRP and osteoarthritis does exist but is dependent on body mass index." (PMID 27327646, 2016). "Immunohistochemical staining revealed that compared with the osteoarthritis synovium, CRP was more abundantly expressed in the lining and sublining areas of the RA synovium." (PMID 25889630, 2015). "Recent studies have indicated that the correlation between CRP levels and osteoarthritis involves other variables besides the disease state." (PMID 19682376, 2009). "Canine serum CRP has earlier been studied as a marker of disease-activity in osteoarthritis (OA), where only slightly elevated levels were observed." (PMID 16987405, 2006). "Furthermore, CRP, IL-6, and TNF-α were found to be reduced by resistance and neuromuscular training in osteoarthritis (OA) patients with pain caused by physical dysfunction." (PMID 41598488, 2026). "Our patients present chronic OM caused by arthrosis, so is not surprising that canonical inflammatory markers such as CRP and PCT were not significantly elevated in our OM patients compared to not-infected patients." (PMID 39125464, 2024). "The detection of autoantibodies (including RA, A-CCP, CRP) in RA patients is an identification that distinguishes the disease from other inflammatory arthritis, such as psoriatic arthritis, reactive arthritis and osteoarthritis." (PMID 33397492, 2021). "In osteoarthritis, CRP or ESR was within the normal range, and these results suggest that systemic inflammation may not exist in patients with OA." (PMID 34830606, 2021). "SNPs of the CRP gene (in the order of rs2794521, rs1800947, and rs1130864) developed into 5 out of 8 possible haplotypes, which captured 85–95% of the genetic variance in osteoarthritis patients and controls." (PMID 34073132, 2021). "Moreover, other osteoarthritis-predictive inflammatory markers such as C-reactive protein (CRP) level and leukocyte count increased with increasing serum ALP levels." (PMID 33261160, 2020). "CRP has also been described as an assessment factor of osteoarthritis." (PMID 31209645, 2019). "The aim of this study was to evaluate whether measurement of serum C-reactive protein (CRP) concentration could be used to discriminate between dogs with suppurative arthritis and osteoarthritis (OA)." (PMID 27793205, 2016). "Additionally, another study showed that genetically elevated CRP levels contribute to osteoarthritis severity." (PMID 27327646, 2016). "It has also been reported that elevations in CRP may reflect events that may precede but ultimately lead to radiographic progression in osteoarthritis." (PMID 23452411, 2013).